SCYGR9 (small cysteine and glycine repeat containing 9 (pseudogene))
Description:
In the hair cortex, hair keratin intermediate filaments are embedded in an interfilamentous matrix, consisting of hair keratin-associated proteins (KRTAP), which are essential for the formation of a rigid and resistant hair shaft through their extensive disulfide bond cross-linking with abundant cysteine residues of hair keratins. The matrix proteins include the high-sulfur and high-glycine-tyrosine keratins.
Synonyms: KRTAP28p1; KRTAP28-9
Gene: Unprocessed pseudogene on chromosome 2 (227,587,237 to 227,587,515, reverse strand). Ensembl gene ENSG00000285843.